HMOX1 (heme oxygenase 1)
Diseases named in the same sentence as HMOX1 in open-access papers (continued):
Sharing a sentence is not in itself a finding about the gene and the disease.
Hyperglycemia (122 papers, 2009 to 2026). An increased concentration of glucose in the blood. "The present study showed that tyrosol, a phenylethanoid compound, suppresses accumulation of intracellular reactive oxygen species (ROS) caused by hyperglycemia, most plausibly by promoting heme oxygenase-1 (HO-1) expression in skeletal muscle cells." (PMID 31474865, 2019). "Collectively, these data suggested that the upregulated expression of Hk2, Ppargc1a, Sorbs1, and Hmox1 might be implicated in the improvement of hyperglycemia and insulin resistance in the exercise GK rats." (PMID 31338039, 2019). "Heme oxygenase-1 (HO-1) produced by MSCs exhibits antioxidant properties and protects islets from hyperglycemia-induced oxidative stress.HO-1 acts via the Nuclear factor erythroid 2-related factor 2 (NRF2) signaling pathway." (PMID 37761001, 2023). "Heme oxygenase 1 overexpression suppresses hyperglycemia-induced gene expression of IL1β, IL6, and MCP1." (PMID 31616304, 2019). "Of them, heme oxygenase-1 is highly inducible in response to a variety of chemical and physical stressors including hypoxia, hyperoxia, hyperglycemia and pro-inflammatory cytokines, and it is considered to be a reliable and sensitive marker of cell stress." (PMID 27936224, 2016). "In particular, rapid histone H3K9/K14 hyperacetylation is associated with enhanced expression of HMOX1 (heme oxygenase (decycling) 1), IL-8, and matrix metalloproteinase 10 (MMP-10) in HAECs exposed to hyperglycemia." (PMID 26015812, 2015). "Palsamy and Subramanian reported that during hyperglycemia-mediated oxidative stress, the expression of Nrf2 and its downregulatory enzymes like heme oxygenase- 1 were significantly decreased in the renal tissues of diabetic rats." (PMID 22483164, 2012). "In this study, the upregulation of HMOX1 in the DFS group may represent a compensatory mechanism: sustained hyperglycemia exacerbates oxidative damage, and elevated HMOX1 expression protects cells against ROS‐induced injury." (PMID 41503916, 2026). "However, during the development of diabetic retinopathy, various factors, such as oxidative stress and inflammatory responses induced by long-term hyperglycemia, can lead to downregulation of HMOX1 expression." (PMID 40282274, 2025). "Chronic hyperglycaemia, characterised here by elevated HbA1c, may suppress HMOX1 through mechanisms involving oxidative damage and altered transcriptional regulation." (PMID 40502600, 2025). "In addition, hyperglycemia and hyperinsulinemia were more pronounced in female adipocyte-specific HMOX1 knockout mice fed both normal and high-fat diets." (PMID 39873298, 2025). "In addition, hyperglycemia suppressed expressions of heme oxygenase 1 (HO-1) and SIRT1, which are restored by treatment with HDAC2 siRNA." (PMID 36900446, 2023). "Furthermore, in diabetic rats, up-regulation of HMOX1 increases serum bilirubin, reduces superoxide anion and endothelial sloughing induced by hyperglycemia." (PMID 32082188, 2020). "High glucose exposure leads to induction of heme oxygenase-1 gene expression and enzyme activity in islets in accordance with elevation in intracellular peroxide concentration, while chronic hyperglycemia results in a decrease in heme oxygenase activity in rat models." (PMID 27936224, 2016). "In addition, increased HMOX1 expression protects rats from hyperglycemia and insulin resistance." (PMID 39873298, 2025). "HIF1A, which expresses many hypoxia-induced genes, is also upregulated by hyperglycemia and consequently induces VEGF and HMOX1, thereby promoting angiogenesis and tumor growth." (PMID 38200154, 2024). "Melatonin treatment reversed the harmful effects of hyperglycemia on EPC through adenosine monophosphate–activated protein kinase-related mechanisms to increase eNOS phosphorylation and heme oxygenase-1 expression." (PMID 36077238, 2022). "Remarkably, deleting heme oxygenase 1 (HMOX1) in hepatocytes protected mice from NAFLD and hyperglycemia by increasing H2O2-mediated PTP1B inactivation." (PMID 33276146, 2021).
Hyperglycemia (continued). "The mRNA expression and activity of heme oxygenase-1 (HO-1) and MnSOD increased, and GSH-Px activity increased during short-term hyperglycemia; as the disease progressed the mRNA expression and activity of both decreased, accompanied by an increase in MDA and a decrease in GSH levels." (PMID 36824356, 2023). "Other studies indicate that heme oxygenase 1 (HO1) can enhance adiponectin expression and reduce hyperglycemia and insulinemia in female mice and increase vascular function and insulin sensitivity and that Prx-2 increases adipogenesis and Prx3 promotes adiponectin expression." (PMID 36830032, 2023). "Moreover, heme oxygenase 1 (HMOX1) deletion in hepatocytes increased H2O2-mediated PTP1B inactivation, protecting mice from NAFLD and hyperglycemia." (PMID 37106795, 2023). "Long-term hyperglycemia exerts the deleterious effects through overproduction of ROS that outweighs their degradation by antioxidant defense systems such as superoxide dismutase (SOD), catalase (CAT), heme oxygenase-1 (HO-1), and thioredoxin (Trx)." (PMID 25525607, 2014). "Additionally, overexpression of Hmox1 in adipose tissue does not protect against high fat diet-induced insulin resistance in mice, whereas in streptozotocin-induced diabetic rats, chronic induction of HO-1 by hemin reduces hyperglycemia and improves glucose metabolism." (PMID 32992485, 2020).
melanoma (116 papers, 2008 to 2026). A malignant, usually aggressive tumor composed of atypical, neoplastic melanocytes. "For instance, hyperforin treatment in melanoma cells harboring BRAFV600E mutation induces heme oxygenase-1 (HMOX1) expression, increases transferrin expression, and lowers glutathione peroxidase-4 to trigger iron-dependent lipid peroxidation and autophagy." (PMID 41009046, 2025). "IF analyses for Hmox1 and Ftl1 revealed that Roxadustat treatment promoted the expression of Hmox1 and caused the degradation of Ftl1 compared to the melanoma group." (PMID 39814705, 2025). "A375 melanoma cells were transfected with plasmids, encoding endonuclease Cas9 and guide-RNAs specific for HMOX1 (see Section 2)." (PMID 37760834, 2023). "This study aims to explore the association of inducible heme oxygenase 1 (HMOX-1) with nuclear BRAFV600E in promoting melanoma aggressiveness." (PMID 35053476, 2022). "Complement component 3a receptor 1 (C3aR1) antagonists restrained neutrophil mobilization, and melanoma-bearing C3aR1-deficient mice had reduced tumor growth and frequency of heme oxygenase 1 (HO-1) expressing monocytic blood precursors of HO-1+ TAMs." (PMID 35158779, 2022). "The expression of the NFE2L2 and HMOX1 genes, encoding the NRF2 and HO-1 proteins, respectively, was analyzed only for the melanoma cells treated with hyperforin salt, due to the problem with the purity of RNA isolated from cells treated with HpExs, rich in phenolic compounds." (PMID 36771178, 2023). "HMOX-1 association with aggressive features and survival was studied in 406 TCGA melanoma samples." (PMID 35053476, 2022). "HMOX1 has also been implicated in PD1-involved exhausted T-cell metabolic regulation in melanoma." (PMID 36189226, 2022). "In this context, the nuclear BRAFV600E/HMOX-1/AKT axis is associated with melanoma aggressiveness." (PMID 35053476, 2022). "Taken together, these findings showed an upregulation of Hmox1, downregulation of Gpx4, and an induction of ferroptosis in osteocytes by melanoma cells." (PMID 39814705, 2025). "A high-fructose diet upregulates heme oxygenase-1 (HO-1) expression, which makes mouse melanoma immune checkpoint inhibitor treatment resistant, and the use of HO-1 small-molecule inhibitors is effective in alleviating resistance." (PMID 40549205, 2025). "Hif1α overexpression significantly increased Hmox1 expression in untreated cells, and after treatment with melanoma-derived CM." (PMID 39814705, 2025). "Osteocytes treated with melanoma CM also showed increased Hmox1 expression, but Gpx4 expression was upregulated in melanoma CM-treated MLO-Y4 cells." (PMID 39814705, 2025). "In the context of melanoma-induced osteocyte ferroptosis, our findings suggest that the Hif1α/Hmox1 axis plays a crucial role." (PMID 39814705, 2025). "Immunofluorescence assays for Hmox1 also confirmed the up-regulation of Hmox1 in melanoma CM-treated MLO-Y4 cells." (PMID 39814705, 2025). "The knockdown of Hmox1 reversed the effects of melanoma-derived conditioned medium (CM), including the reduction in Gpx4 levels and the degradation of Ftl1." (PMID 39814705, 2025). "Znpp treatment significantly reduced the upregulation of Hmox1, induced by melanoma-derived CM in comparison to B16F10 + DMSO." (PMID 39814705, 2025). "Next, we generated Hmox1 knockdown in osteocytes using shRNA and exposed the cells to melanoma-derived CM." (PMID 39814705, 2025). "A significant increase in Hmox1 expression within tibial osteocytes was observed in the melanoma group compared to controls." (PMID 39814705, 2025). "While our investigation sheds light on the role of the Hif1α-Hmox1 axis in melanoma-induced osteocyte ferroptosis, it focuses primarily on a subset of molecular pathways and regulatory mechanisms." (PMID 39814705, 2025). "To verify the importance of Hmox1 in melanoma-derived CM-induced osteocyte ferroptosis, we used the ferroptosis inhibitor Fer-1 and the Hmox1 inhibitor Znpp." (PMID 39814705, 2025).
melanoma (continued). "Mechanistically, fructose activated cryoprotection in melanoma cells by inducing heme oxygenase-1 (HO-1) expression, allowing them to be resistant against immune-mediated killing during ICB therapy." (PMID 38711514, 2024). "Melanoma cells were shown to undergo ferroptosis through the Keap1-NRF2-heme oxygenase 1 (Hmox1) pathway when Gel@WA-cRGD inhibited GSH and GPX4 expression." (PMID 38853203, 2024). "Further analyzes revealed overexpression of heme oxygenase 1 and the activation of the AKT pathway in association with nuclear BRAF V600E and cell proliferation in BRAF inhibitor resistant melanoma cells." (PMID 39272837, 2024). "The expression of the NFE2L2 and HMOX1 genes correlates with the content of the NRF2 and HO-1 proteins in melanoma cells treated with hyperforin salt, except for WM115 cells cultured in hypoxia." (PMID 36771178, 2023). "Fructose consumption has also been shown to upregulate the cytoprotective enzyme heme oxygenase-1 (HO-1), which contributed to resistance to checkpoint blockades in melanoma mouse model." (PMID 38139110, 2023). "We propose a strong role for HMOX1 in metabolic plasticity and the ability of melanoma cells to switch metabolic phenotypes, as these cells adapt or initiate mechanisms to resist BRAF/MEK inhibitor treatment." (PMID 37176114, 2023). "Inactivation of HMOX1 by administration of the HMOX1 inhibitor SnPPIX allowed, in fact, a significant and complete recovery of melanoma cell proliferation and metabolic activity." (PMID 36982774, 2023). "Inhibiting either Nrf2 or its target gene, HMOX-1 (heme oxygenase 1 gene) prevents melanosphere formation, an indicator of cell tumorigenic potential, in melanoma cell lines." (PMID 36747120, 2023). "The aim of our study is to determine the role of nuclear BRAFV600E and its newly identified partner, HMOX1, in melanoma aggressiveness and drug resistance." (PMID 35053476, 2022). "In the present study, upregulation of heme oxygenase 1 (HO-1) was shown for the first time in primary BRAFV600E melanoma cells adapted to physiological oxygen tension and hypoxia to limit the efficacy of Vemurafenib/PLX4032." (PMID 35740068, 2022). "We identified the mechanism by which drug resistance is developed via the nuclear localization of BRAFV600E and its partner HMOX1 in melanoma tissues and cell lines." (PMID 35053476, 2022). "Mechanistic studies revealed that HMOX-1 was associated with nuclear BRAFV600E localization, thus promoting melanoma proliferation via a persistent activation of the AKT pathway." (PMID 35053476, 2022). "Previously, our group showed that heme-degrading enzyme heme oxygenase-1 (HO-1) can be upregulated in melanoma and increase its aggressiveness." (PMID 35408953, 2022). "The highest correlations observed with HMOX-1 in patients with melanoma were with FZD2 (rho = 0.54), KEAP1 (rho = 0.59), MAPK13 (rho = 0.68), the “ferroptosis” gene FTL (rho = 0.58), and CHUK (rho = −0.50)." (PMID 35053476, 2022). "Induction of heme oxygenase 1 (HO-1) favors immune-escape in BRAFV600 melanoma cells treated with Vemurafenib/PLX4032 under standard cell culture conditions." (PMID 35740068, 2022). "The resistance to BRAFV600E inhibitors is also correlated with the high expression of HMOX-1 in a melanoma mouse model and in a melanoma patient database." (PMID 35053476, 2022). "As the development of melanoma is facilitated by a high expression level of HO-1, we compared the expression of Hmox-1 in MIC+ subsets and MIC− cells." (PMID 35408953, 2022). "Further study of HMOX-1 knockdown or BRAFV600E overexpression in melanoma cells suggested a role for HMOX-1 in the regulation of cell proliferation in vivo and in vitro." (PMID 35053476, 2022). "Bryonia alba was also found to suppress the development of B-16 melanoma cells in vitro, by activating heme oxygenase 1 (HO-1), and lowering nitric oxide (NO) levels." (PMID 35729949, 2022).
melanoma (continued). "Our results provide the first evidence that nuclear BRAFV600E plays a critical role in the regulation of HMOX-1 protein overexpression in resistant melanoma cells." (PMID 35053476, 2022). "Since Hmox1 has a pivotal role in heme oxidation and iron metabolism, crucial in ferroptosis, our findings suggest Hmox1 could play a critical role in melanoma metastasis-induced osteocyte ferroptosis." (PMID 39814705, 2025). "Through leveraging gene signatures in predicting the durability of drug response, this study also identified the expression levels of the genes MMP2, SPARC, and HMOX1 as having a good predictive value in predicting the emergence of chemoresistance to BRAF/MEK inhibitor therapy in melanomas." (PMID 37176114, 2023). "The pattern of expression of this stress response protein has also been quite variable in different human melanoma studies, but it is worth noting that in our study, the HMOX1 protein pattern of expression was induced exclusively by CINN-EO, being absent in untreated metastatic melanoma cells." (PMID 36982774, 2023). "Moreover, HMOX-1 overexpression in A375 melanoma cells increases tumor volume, whereas silencing HMOX-1 reduces tumor growth in mouse models." (PMID 36747120, 2023). "HMOX1 is one of the driving forces in melanoma invasion and migration." (PMID 36747120, 2023). "Targeting HMOX-1 could be a novel method for treating melanoma patients who develop BRAF inhibitor resistance." (PMID 35053476, 2022). "Thus, to the best of our knowledge, the present study provides the first evidence of a possible role of nuclear BRAFV600E/HMOX-1/AKT in melanoma resistance." (PMID 35053476, 2022). "Therefore, the combination of specific HMOX-1 inhibitors with BRAFV600E inhibitors is anticipated to reduce melanoma aggressiveness and improve BRAFV600E inhibitor-based therapies." (PMID 35053476, 2022). "These targets could include thioredoxin secretion, heme oxygenase 1, and cell-surface expression of heat shock protein 70, previously shown to play a role in the immune response to melanomas." (PMID 35326683, 2022). "Next, we used a mouse xenograft model of melanoma to examine whether overexpression of nuclear BRAFV600E upregulates HMOX-1 protein expression." (PMID 35053476, 2022). "Finally, public transcriptomic databases were used to validate the role of the HMOX-1 gene in response to BRAF inhibitor treatment in melanoma xenograft models and patients." (PMID 35053476, 2022). "Furthermore, we explored the role of HMOX-1 in promoting melanoma aggressiveness using a xenograft mouse model." (PMID 35053476, 2022). "The elevated expression of HMOX1 has been seen in multiple cancers that also include melanoma." (PMID 35326683, 2022). "In addition, compounds 3 and 5 strongly induced oxidative injury to melanoma cells as measured by TUNEL colocalization with heme oxygenase-1 (HO1)." (PMID 34430045, 2021). "In this study we could demonstrate, that treatment with BOZ led to Caspase-3 and Heme Oxygenase-1 (HO-1) activation in both cell lines, and could upregulate the expression of Claspin only in melanoma cells." (PMID 32868799, 2020). "In addition, the high expression of HMOX1 gene was observed in the culture of human melanoma cells, confirming the induction of cellular oxidative stress during harmful insults." (PMID 32095238, 2020). "Ultraviolet radiation (UVR) is estimated to be responsible for the appearance of approximately 65% of all melanomas, while heme oxygenase 1 (HO-1), the inducible form of heme oxygenase, can be induced in response to diverse cellular stress signals such as UVR and reactive oxygen species (ROS)." (PMID 30634993, 2019). "The overexpression of HMOX1 has been observed in liver cancer, pancreatic cancer, and melanomas." (PMID 21843314, 2011). "Furthermore, Hmox1 knockdown reduced the excessive autophagy induced by melanoma-derived CM." (PMID 39814705, 2025).